VCAM1 (vascular cell adhesion molecule 1)
Diseases named in the same sentence as VCAM1 in open-access papers (continued):
Sharing a sentence is not in itself a finding about the gene and the disease.
cerebral malaria (3 papers, 2011 to 2022). A sequestration of Plasmodium falciparum in the brain, which can cause coma and/or seizures. "In experimental cerebral malaria reports, the use of rapamycin restricts the cytoadherence of infected RBCs on endothelial cells by VCAM-1 and ICAM-1 reduction." (PMID 35735506, 2022). "It is also possible that HIV-infected children are at increased risk of developing cerebral malaria because of an increased production of nitric oxide synthase, ICAM-1 and VCAM-1 with HIV infection." (PMID 21235797, 2011). "Moreover, the fungal ethanolic extract of Trichoderma stromaticum helps in reducing inflammation in experimental cerebral malaria by reducing the expression of VCAM-1 and ICAM-1, thus protecting the blood-brain barrier’s integrity." (PMID 35735506, 2022).
chronic lymphocytic leukemia (3 papers, 2016 to 2024). "Inhibition of Syk, or Syk knockdown, suppressed VCAM-1-induced Akt activation and cell adhesion in chronic lymphocytic leukemia cells." (PMID 26848618, 2016). "Engagement of the α2β1 integrin by stromal VCAM1 and activation of CXCR4 together promote survival signaling via the Syk tyrosine kinase in chronic lymphocytic leukemia (CLL)." (PMID 38279122, 2024). "In chronic lymphocytic leukemia cells, ephrin-A4 activation by EphA2-Fc significantly reduced cell adhesion to fibronectin-, collagen-, laminin-, ICAM-1-, and VCAM-1-coated surfaces." (PMID 28851287, 2017).
cystic fibrosis (3 papers, 2017 to 2023). Autosomal recessive disorder caused by pathogenic variants in the CFTR gene (cystic fibrosis transmembrane conductance regulator), which encodes a chloride and bicarbonate channel expressed in epithelial cells, and follow the diagnosis criteria. "SNPs in the VCAM-1 and ARFGEF2 genes, a deletion in the CTFR gene and CNVs in the HLA gene were found to be associated with cases of sickle cell anaemia, cystic fibrosis and rheumatoid arthritis, respectively." (PMID 30084865, 2019).
cytomegalovirus infection (3 papers, 2007 to 2019). A herpesvirus infection caused by Cytomegalovirus. "VCAM-1 induction has been observed following herpes simplex virus and human cytomegalovirus infection." (PMID 17485528, 2007). "Pathways: Human cytomegalovirus infection and Blood-Brain Barrier and Immune Cell Transmigration: VCAM-1/CD106 Signaling Pathways; GO: G protein-coupled receptor activity and ubiquitin protein ligase binding." (PMID 31850854, 2019). "Nonetheless, it is known that HCMV infection of endothelial cells induces the expression of adhesion molecules ICAM-1 and VCAM-1 that serve to magnify transendothelial cell migration of inflammatory cells including monocytes." (PMID 22570607, 2012).
Fabry disease (3 papers, 2013 to 2024). Fabry disease (FD) is a progressive, inherited, multisystemic lysosomal storage disease characterized by specific neurological, cutaneous, renal, cardiovascular, cochleo-vestibular and cerebrovascular manifestations. "In Fabry disease, elevated levels of VCAM1 have been detected in peripheral blood, and Gb3 stimulated endothelial cells." (PMID 39596318, 2024). "Together, these findings underscore the importance of the VLA4/VCAM1 axis in the infiltration of immune cells into tissues, suggesting it plays a pivotal role in the pathophysiology of the Fabry disease." (PMID 39596318, 2024). "In the context of Fabry disease, elevated levels of adhesion molecules such as VLA4, CR3, ICAM1, VCAM1, and PECAM1 in the bloodstream are closely linked to disease severity." (PMID 39596318, 2024). "Another study indicates that excess Gb3 on exposed endothelial cells leads to the upregulation of adhesion molecules like ICAM1 and VCAM1 in Fabry disease." (PMID 39596318, 2024). "There was a trend for low serum levels of IL-6 and high serum levels of TNF-α and high-sensitive CRP in Fabry patients; plasma concentrations of soluble VCAM-1 were significantly higher in Fabry disease patients than in healthy volunteers (p = 0.02)." (PMID 24207059, 2013). "Furthermore, Gb3 stimulation of endothelial cells has been shown to induce upregulation of VCAM1 in the context of Fabry disease." (PMID 39596318, 2024). "In Fabry disease, elevated levels of ICAM1, VCAM1, and PECAM1 have been observed in peripheral blood cells." (PMID 39596318, 2024). "In addition, circulating monocytes in Fabry disease show upregulation of MHC II expression, alongside significantly elevated levels of soluble ICAM 1 and VCAM1." (PMID 39596318, 2024). "Moreover, Gb3 upregulates VCAM-1 (Vascular cell adhesion protein 1) but not ICAM-1 (Intercellular Adhesion Molecule 1) expression in HMiVECs, indicating a pro-inflammatory phenotype in Fabry disease." (PMID 39125842, 2024).
gastritis (3 papers, 2020 to 2021). Inflammation of the stomach. "The verification results of the GSE5081 dataset showed that except for DUOX2 and VCAM1, the other 13 genes were significantly upregulated in gastritis, which was consistent with the results in the GSE60427 dataset." (PMID 34471638, 2021). "The results showed that except for DUOX2 and VCAM1, the other 13 genes were significantly upregulated in gastritis compared to normal, which was consistent with the results in the GSE60427 dataset." (PMID 34471638, 2021). "VCAM-1, a molecule described as an oncogene in adults, is overexpressed in serum of children with H. pylori-induced gastritis, representing a potential non-invasive biomarker of H. pylori-induced damage in both symptomatic and asymptomatic children." (PMID 32117120, 2020). "In children, it was described that the serum concentrations of VCAM-1 were higher in symptomatic children with HPI-associated gastritis compared to non-infected children and confirmed that the serum levels of VCAM-1 correlated with HI-induced gastric inflammation and damage." (PMID 33763365, 2021).
gestational diabetes (3 papers, 2021). Carbohydrate intolerance first diagnosed during pregnancy. "Significantly increased serum concentrations of soluble VCAM-1 have been noted in patients with gestational diabetes mellitus (GDM) and type 1 diabetes (T1D) compared with the control group." (PMID 34944571, 2021).
Graves disease (3 papers, 2020 to 2025). Graves' disease is an autoimmune disorder that leads to overactivity of the thyroid gland (hyperthyroidism).It is caused by an abnormal immune system response that causes the thyroid gland to produce too much thyroid hormones. "Patients with Graves’ disease had a higher mean VCAM-1 level than those with normal thyroid function." (PMID 33051540, 2020). "Subjects with Graves’ disease also had a higher serum VCAM-1 level (1309 ± 292 vs. 1009 ± 168 ng/mL, P < 0.001)." (PMID 33051540, 2020). "It has been reported that a high circulating VCAM-1 level was detected in patients with Graves’ disease, and the level was positively correlated with the free T4 levels." (PMID 33051540, 2020). "Patients with Graves’ disease had a higher VCAM-1 level (1309 ± 292 vs. 1009 ± 168 ng/mL, P < 0.001) and a lower ABI (0.98 ± 0.11 vs. 1.06 ± 0.10, P < 0.001) than those with euthyroidism." (PMID 33051540, 2020). "In the present study, only the VCAM-1 level, but not the CRP level, was significantly increased in patients with Graves’ disease." (PMID 33051540, 2020).
hepatitis C (3 papers, 2018 to 2024). "A preliminary pilot study was carried out on the effect of δ-tocotrienol feeding in hepatitis C patients on six protease subunits (X, Y, Z, LPM7, LMP2 and LMP10), ICAM-1, VCAM-1, and TNF-α using total blood mRNA of these patients." (PMID 29606130, 2018). "The total RNAs obtained from δ-tocotrienol treated hepatitis C patients showed significant decrease in expression of pro-inflammatory cytokines such as TNF-α (47%; P < 0.001), VCAM-1 (22%; P < 0.01)." (PMID 29606130, 2018). "The total RNAs obtained from plasmas of δ-tocotrienol treated hepatitis C patients showed significant decreases in the expression of TNF-α (47%) and VCAM-1 (22%) pro-inflammatory cytokines." (PMID 29606130, 2018). "In addition to that, effect of δ-tocotrienol on expression of proteasome subunits (X, Y, Z, LMP7, LMP2, LMP10), ICAM-1, VCAM-1, and TNF-α using total RNAs derived from plasmas of hepatitis C patients was investigated." (PMID 29606130, 2018). "Moreover, results of plasma total mRNAs after δ-tocotrienol feeding to hepatitis C patients revealed significant inhibition in the expression of pro-inflammatory cytokines (TNF-α, VCAM1, proteasome subunits) and induction in the expression of ICAM1 and IFN-γ after post-treatment." (PMID 30031388, 2018).
hippocampal atrophy (3 papers, 2017 to 2026). "VCAM-1 is thought to reflect endothelial activation and chronic inflammation, suggesting that it may impact vascular dysfunction and reduced perfusion, which can be critical mediators of hippocampal atrophy." (PMID 40842651, 2025).
HIV-1 infection (3 papers, 2011 to 2024). The type species of lentivirus and the etiologic agent of acquired immunodeficiency syndrome (AIDS). "For example, IL-1α, IL-10, CCL2, LMNA, and VCAM1, the target genes identified in this study, have been reported to be associated with HIV-1 infection and pathogenesis." (PMID 38110484, 2023).
Hypoglycemia (3 papers, 2014 to 2026). A decreased concentration of glucose in the blood. "Others reported increased levels of VEFGA, ICAM1 and VCAM1 50 min post hypoglycemia (3.2 mmol/L) in T2D." (PMID 41596469, 2026). "Our results are in accordance with others who showed no changes in ICAM1 and VCAM1 post hypoglycemia." (PMID 41596469, 2026). "Ischemic insults, including hypoxia and hypoglycemia, trigger a signaling cascade that upregulates the expression of endothelial adhesion molecules, such as intercellular adhesion molecule-1 (ICAM-1) and vascular cell adhesion molecule-1 (VCAM-1)." (PMID 39063126, 2024). "In addition to the disruption of VE cadherin, a modest (not statistically significant) increase of VCAM-1 (both membrane and soluble fractions) was observed following 3 and 24 h exposure to hypoglycemia." (PMID 24708805, 2014).
intestinal inflammation (3 papers, 2021 to 2024). "Additionally, studies have found that blocking ICAM-1 and VCAM-1 can reduce leukocyte adhesion in rat ileitis, indicating their potential in the treatment of intestinal inflammation." (PMID 38660311, 2024).
ischemia reperfusion injury (3 papers, 2010 to 2025). Adverse functional, metabolic, or structural changes in ischemic tissues resulting from the restoration of blood flow to the tissue (reperfusion), including swelling; hemorrhage; necrosis; and damage from free radicals. "Animal studies have shown that XFZY can reduce intracellular adhesion molecule-1 (ICAM-1) and vascular cell adhesion molecule-1 (VCAM-1), thereby reducing the inflammatory response induced by ischemia-reperfusion injury (IRI)." (PMID 36437831, 2022). "Vascular cell adhesion molecule-1 (VCAM-1) is upregulated in ischemia reperfusion injury (IRI), persisting after restoration of blood flow." (PMID 20877722, 2010).
ischemic cardiomyopathy (3 papers, 2022 to 2025). Ischemic cardiomyopathy is a cardiomyopathy in which a weakness in the muscle of the heart due to inadequate oxygen delivery to the myocardium with coronary artery disease being the most common cause. "Clinical investigations have also indicated that VCAM-1 level is elevated in patients with ischemic cardiomyopathy." (PMID 36467095, 2022). "Moreover, the mRNA expression of VCAM-1 is significantly increased in patients with ischemic cardiomyopathy." (PMID 36467095, 2022).
ischemic disease (3 papers, 2016 to 2022). Lack of blood supply to an area of the body, resulting in impairment of tissue oxygenation. "Moreover, the exciting therapeutic efficacy of VCAM-1+CV-MSCs on ischemic nude mice not only provided a novel strategy for cell-based therapy of ischemic diseases, but also a hint for banking appropriate MSCs for clinical usage." (PMID 27044487, 2016).
lung disease (3 papers, 2020 to 2025). "Similarly, elevated levels of soluble VCAM-1, E-selectin, and ICAM-1 have been found in patients with SSc renal crisis, but not in those with SSc-associated pulmonary disease." (PMID 40094867, 2025). "In IIM, cohort studies have demonstrated higher levels of circulating VCAM-1, ET-1, thrombomodulin, and plasminogen activator inhibitor-1 in IIM patients with ILD compared to IIM without lung disease." (PMID 40055821, 2025).
meningioma (3 papers, 2022 to 2025). A generally slow growing tumor attached to the dura mater. "Interaction with tissue stem cells through the Itgb1/Vcam1 pathway may reflect the complex role of T cells in regulating the meningioma tumour microenvironment, promoting immune responses and inhibiting or promoting tumour growth." (PMID 40046334, 2025). "Meningiomas Group: ICAM-1, E-Selectin, and MMP-9 were the most expressed markers, while PAI-1 and VCAM-1 exhibited less expression." (PMID 38306519, 2024).
meningitis (3 papers, 2022 to 2023). A disorder characterized by acute inflammation of the meninges of the brain and/or spinal cord. "These are knowingly associated with neuroinflammation, compromising BBB integrity and favoring leukocyte transmigration, such as seen in meningitis and in autoimmune encephalomyelitis; in endothelial progenitor cells in vitro, NF-kB activation is known to induce expression of both VCAM-1 and ICAM-1." (PMID 36361571, 2022).
nasal polyps (3 papers, 2011 to 2021). "Apart from VCAM1, P-selectin has been suggested primarily to promote the recruitment of eosinophils in nasal polyp tissues." (PMID 24995349, 2014). "Additional staining showed increased expression of VCAM1 in sections of nasal polyps compared to the inferior turbinates and similar expression of ICAM1 (data not shown)." (PMID 24995349, 2014). "Others reported an increased expression of VCAM1 in nasal polyps and we also could see this on protein level." (PMID 24995349, 2014). "Due to the fact that E-selectin, P-selectin, PSGL1, ICAM1, and VCAM1 are expressed by inflamed endothelial cells, we determined the expression of CD31, a specific endothelial cell marker, in nasal polyps and inferior turbinates of 7 patients." (PMID 24995349, 2014). "Expression levels of PSGL1, ICAM1, and VCAM1 did not significantly differ between nasal polyps and inferior turbinates." (PMID 24995349, 2014).
rhinitis (3 papers, 2018 to 2021). An inflammation of the mucous membrane lining the nose, usually associated with nasal discharge. "In the present study, we also noticed a significant reduction of CAM levels in patients with moderate-severe forms compared to patients with mild rhinitis (VCAM-1 p = 0.037, ICAM-1 p = 0.001 and E-selectin p = 0.002)." (PMID 30008985, 2018). "We observed a significant reduction in VCAM-1 and ICAM-1 levels in patients with moderate-to-severe forms, compared with patients with mild rhinitis (p = 0.03, p = 0.01, respectively)." (PMID 35011854, 2021). "The clinical (rhinitis symptoms and total symptoms score (TSS), type of sensitization) and biological evaluation (total IgE, eosinophils, ICAM-1, VCAM-1, and E-selectin) as well as fractionate nitric oxide in exhaled air (FeNO) measurement was performed before and after treatment." (PMID 30008985, 2018).
skin cancer (3 papers, 2023 to 2026). "Here we use single-cell and spatial expression approaches to identify a distinct TREM2+ VCAM1+ macrophage population within the highly proliferative neighborhood of naïve human BCCs, which we call skin cancer-associated macrophages (SCAMs)." (PMID 37164949, 2023). "Consistent with M2-like macrophages in skin tumors, sub-cluster 2 showed high expression of M2-like macrophage markers, including Mgl2, Cx3cr1, Vcam1, Maf, Ccl8, and Cxcl10." (PMID 40282557, 2025). "Also, the available data suggest that the expression of ICAM-1 and VCAM-1 in fibroblasts, which are generally absent or low, can be upregulated by inflammatory cytokines, raising the question of their possible role in tumorigenesis and tumor spread in skin cancers." (PMID 41597444, 2026).
squamous cell carcinoma (3 papers, 2022 to 2025). A carcinoma arising from squamous epithelial cells. "Pre‐treatment levels of both VCAM‐1 and ICAM‐1 were higher in patients with adenocarcinoma than in patients with squamous cells carcinoma." (PMID 34390488, 2022).
steatosis (3 papers, 2023 to 2024). Increased lipid within the cytoplasm of cells. "Steatosis can also increase the expression of cell adhesion molecules, such as VCAM-1, by the liver sinusoidal endothelial cells, thereby recruiting monocytes into the liver and promoting the pathogenesis of MASLD50." (PMID 38553537, 2024). "Consistent with the findings from the HCD-model, neither steatosis nor fibrosis was altered in HSC-specific VCAM-1 deficient mice, as compared to the control mice." (PMID 36902241, 2023). "Despite the expression of VCAM-1 in activated HSCs in NASH, HSC-specific VCAM-1 deficiency did not affect the grade of steatosis and fibrosis upon HCD feeding." (PMID 36902241, 2023).
tendinopathy (3 papers, 2017 to 2022). "Both early and chronic stage tendinopathy tissues expressed markers of vascular endothelial activation (CD31 ICAM1 VCAM1) relative to healthy tendons." (PMID 38655164, 2022). "Stromal fibroblasts from patients with tendinopathy were analyzed for activation markers including podoplanin, CD106 (VCAM-1) and CD248." (PMID 30847027, 2019). "Tissues and cells derived from patients with tendinopathy show increased expression of markers of stromal fibroblast activation including Podoplanin (PDPN), VCAM-1 (CD106) and Endosialin (CD248) compared to healthy tendon tissues and cells." (PMID 28887458, 2017).
thalassemia (3 papers, 2018 to 2025). An inherited blood disorder characterized by a decreased synthesis of one of the polypeptide chains that form hemoglobin. "This systematic review and meta-analysis identifies ICAM-1, VCAM-1, E-selectin, P-selectin, and ET-1 as biomarkers for assessing cardiovascular risk in thalassemia patients, underscoring their potential for early detection and targeted interventions in clinical practice." (PMID 40332500, 2025). "This review highlights ICAM-1, VCAM-1, E-selectin, P-selectin, and ET-1 as key biomarkers for cardiovascular complications in thalassemia." (PMID 40332500, 2025). "A total of 11 articles investigated the levels of VCAM-1 in both thalassemia patients and healthy individuals." (PMID 40332500, 2025). "The VCAM-1 outcome between the two groups showed significant differences and trended higher in thalassemia compared to the healthy control." (PMID 40332500, 2025). "This meta-analysis found that the expression levels of endothelial adhesion molecules, including ICAM-1, VCAM-1, E-selectin, and P-selectin, were significantly elevated in thalassemia patients compared to healthy individuals." (PMID 40332500, 2025). "Our data showed that VCAM-1, VEGF and CD163 are elevated in all patient groups, thus representing markers associated to thalassemia, independently from severity of the disease." (PMID 36699704, 2022). "Accordingly, this systematic review and meta-analysis aims to explore the levels of endothelial biomarkers, including ICAM-1, VCAM-1, E-selectin, P-selectin, vWF, EMPs, NO, NOS, ADMA, and ET-1, in both thalassemia patients and healthy individuals." (PMID 40332500, 2025). "As thalassaemia MPs could induce TF, IL-6, IL-8, ICAM-1, VCAM-1 and E-selectin expression, the potential functional consequences of MPs influence on the adhesion of endothelial cells and monocytes was examined." (PMID 30158562, 2018). "The results showed significantly elevated levels of ICAM-1 (SMD 2.15, 95% CI: 1.09–3.22), VCAM-1 (SMD 2.50, 95% CI: 1.35–3.66), E-selectin (SMD 1.21, 95% CI: 0.92–1.50), P-selectin (SMD 1.62, 95% CI: 0.83–2.42), and ET-1 (SMD 1.23, 95% CI: 0.03–2.42) in thalassemia patients." (PMID 40332500, 2025).